CASR (calcium sensing receptor)
Diseases named in the same sentence as CASR in open-access papers (continued):
Sharing a sentence is not in itself a finding about the gene and the disease.
tumor (continued). "Plotting the proportion of maximally responsive tumor cells as a function of calcium concentration yields a sigmoid dose-response curve with a calculated calcium EC50 value significantly elevated above published reference values for wild-type calcium-sensing receptor (CASR) sensitivity." (PMID 27537691, 2016). "Higher CaSR expression was significantly associated with lethal progression among cases with lower tumor vitamin D receptor expression but not among cases with high tumor vitamin D receptor expression." (PMID 27625611, 2016). "CaSR antagonists can inhibit ERK1/2, PI3K/Akt, and Wnt/β-catenin signaling pathways, thereby reducing the proliferation of tumor cells and promoting apoptosis." (PMID 41522513, 2026). "In recent years, accumulating evidence has shown that CaSR plays an important role in the occurrence and development of various malignant tumors, and that its activation or inhibition may affect the proliferation, apoptosis, invasion, and metastasis of tumor cells." (PMID 41522513, 2026). "As the majority of tumor cells depend on the G2/M checkpoint for DNA repair, the increase of BRCA1 and the elevated percentages of CaSR-overexpressing cells in the LUAD cell lines in G2/M phase imply that these cells possess a more adequate DNA repair process." (PMID 39113697, 2024). "However, it remains unclear how CaSR affects the cell cycle and DNA damage repair in tumor cells." (PMID 39113697, 2024). "Out of 21 ICD-related genes with notably different expressions, seven genes, namely ROCK1, BCL2, TLR2, TLR9, AGER, CASR, and P2RX7, were found to have decreased expression in tumor samples, while the rest were upregulated." (PMID 37932362, 2023). "Although assessment of tumor characteristics and/or progression patterns are not available in the EHRs, we hypothesized that the association of CaSR SNPs with tumors at secondary sites (secondary malignancies) is indicative of the progression of primary tumors to these sites." (PMID 34357109, 2021). "In this set of experiments, both receptors, CaSR and TRPV6, demonstrated similar distribution at immunohistochemistry analysis across the different type of tumour lesions." (PMID 32931488, 2020). "Colocalization of chromogranin and CaSR in the same tumor areas was also observed in CLC and MCRPC cases, and CaSR was expressed in all cases of NEPC." (PMID 32252342, 2020). "In these tumours the expression levels of CaSR and TRPV6 ranged between score 0 and 4 and both calcium receptors appear expressed at the same level in the same tumour." (PMID 32931488, 2020). "Indeed, although Mn2+ is a free ion, its blood half-life is nearly 2 hours long, therefore within the 90 minutes time-frame, tumour regions with high vascularity, permeability and perfusion could be reached by a continuous flux of Mn2+ and retain it with the contribution of CaSR-mediated uptake." (PMID 32931488, 2020). "Thus, CaSR may modulate tumour progression by suppressing E-cadherin/β-catenin complex formation." (PMID 29348629, 2018). "In a cohort of 111 CRC patients, we found significant inverse correlation between CaSR expression and markers of epithelial-to-mesenchymal transition (EMT), a process involved in tumor development in CRC." (PMID 25879211, 2015). "Furthermore, we show that when the CaSR is introduced into an NF‐PNET cell line, not only was the CaSR able to increase intracellular calcium concentrations, but it also significantly reduced cell viability, consistent with evidence that the CaSR may play a tumour suppressor role in certain tissues." (PMID 39579056, 2025). "According to the GEPIA database, there were some LUAD tumor tissues with high CaSR expression, although there was no statistical difference between tumor and normal tissues in LUAD at the overall level." (PMID 39113697, 2024). "A positive correlation was found between the expression of the CaSR and tumor size, regardless of the tumor type (p = 0.001)." (PMID 37511437, 2023).
tumor (continued). "Collectively, the results of this study indicate that there is a positive relationship between CaSR expression and tumor size, irrespective of the tumor surrogate subtype." (PMID 37511437, 2023). "The results revealed a positive correlation between CaSR expression and tumor size, regardless of the tumor surrogate subtype (p = 0.001)." (PMID 37511437, 2023). "Although not all mechanisms by which the CaSR affects tumor growth have been clarified, our study showed a significant positive correlation between tumor size and the expression of the CaSR." (PMID 37511437, 2023). "Among its non-calciotropic roles, where the CaSR sits at the intersection of myriad processes, it has steadily garnered attention as an oncogene or tumor suppressor in different organs." (PMID 32117726, 2020). "This can be probably explained by a delayed hypocalcemic effect of the drug, inability to properly escalate the dose due to drug intolerance, or lack of CaSR sensitivity at the tumor level." (PMID 33112830, 2020). "Therefore, we investigated the role of CaSR on LUAD growth regulation and its mechanism by using human LUAD specimens, A549 cells, and a tumor xenograft model." (PMID 32671062, 2020). "Ca levels inversely correlated with the level of the cancer antigen 19-9 (CA 19-9) tumor marker but not with the carcinoembryonic antigen (CEA) or alpha fetoprotein (AFP) tumor markers or the CaSR genotypes." (PMID 31534963, 2019). "However, in our model, the osteolytic activity of CaSR-WT-transfected MDA-MB-231 was so strong within 19 days, that the tumor invaded almost the whole bone." (PMID 28915604, 2017). "As a major component of the calcium homoeostatic system, the CaSR contributes to the development of CIH by promoting the growth and metastatic properties of tumor cells and/or by promoting the secretion of tumor cell-derived osteolytic factors such as parathyroid hormone-related protein (PTHrP)." (PMID 28764683, 2017). "Furthermore, disrupting the CaSR inhibited growth and increased apoptosis in MMTV-PyMT tumor cells grown ex vivo, again by altering p27kip1 levels and nuclear AIF accumulation respectively." (PMID 27746743, 2016). "We have in fact observed intratumoural heterogeneity in CASR protein localization, although the overall proportion of CASR‐positive and CASR‐negative cells in the microraft arrays is consistent with what we observe in tissue sections from the parental tumours." (PMID 26638194, 2016). "There was no significantcorrelation between tumor CASR mRNA levels and overall tumor weight(Spearman’s rank-order correlation: R = 0.299, P =0.085)." (PMID 26865585, 2016). "In vivo, dearth of CaSR significantly increased expression of proliferation markers and decreased levels of differentiation and apoptotic markers in the colons of CaSR/PTH double knock-out mice confirming the tumor suppressive functions of CaSR." (PMID 25701758, 2015). "In tumor specimens of patients developing bone metastases, CaSR mRNA expression was 7.9-fold higher than in tumor specimens of patients without metastases." (PMID 24576174, 2014). "Tumor specimens from patients with no metastases or with lung metastases expressed CaSR mRNA moderately." (PMID 24576174, 2014). "From the evidence that expression of the CaSR is highest in well differentiated cancers and declines during tumor progression, it can be implied that calcium acting via the CaSR is a chemopreventive rather than a chemotherapeutic agent." (PMID 23340319, 2013). "Hence, we sought to identify a new calcimimetic that biased CaSR signaling towards a distinct intracellular pathway, showing tumor suppression properties similar to CIN, without affecting plasma calcium levels." (PMID 35457141, 2022). "It follows that the vital role of CaSR in tumour progression is not restricted to its participation in tumour cell proliferation; CaSR is also involved in managing subsequent distal metastases of tumours." (PMID 29348629, 2018).
tumor (continued). "To explain this phenomenon, we hypothesized that the osteolysis induced in vivo by the MDA-MB-231 overexpressing the functional CaSR might have favored the release of growth factors such as TGF-β from the bone matrix, which in turn might have favored tumor cell proliferation." (PMID 28915604, 2017). "In addition, the involvement of transcription factors in the reduced expression of the CaSR in neoplasia of parathyroid and colon, for example, are not known." (PMID 27679579, 2016). "Speculatively, a genetic event resulting in parathyroidproliferation while leaving PTH-regulatory systems intact – in this case exemplified byintact CASR expression – could account for a phenotype with relativelylarger tumor size and lower PTH expression per tumor cell." (PMID 26865585, 2016). "Quantification of the CaSR expression in RCC was performed by analyzing tumor and normal tissue specimens from RCC patients without metastases and from patients developing lung or bone metastases within 5 years after nephrectomy (11 patients/category) by quantitative RT-PCR." (PMID 24576174, 2014). "We recognize that positional information and tumour microenvironment context are not preserved in dispersed cell systems and that appropriate subcellular trafficking and activity of the CASR protein might be at least partially dependent upon intact tissue structure." (PMID 26638194, 2016). "Targeting this pathway by inhibiting CaSR signalling via treatment with the CaSR negative allosteric modulator NPS-2143, and mammary gland-specific deletion of the Casr gene, reduced tumour cell proliferation and PTHrP secretion." (PMID 34223822, 2021). "In tumor tissue specimens of RCC patients with bone metastases during 5 years after nephrectomy, we found a distinctly higher expression of CaSR, compared to tumor tissue specimens of patients with no or with lung metastases." (PMID 24576174, 2014). "However, CASR genetic lesions are not found in sporadic PHPT, and multiple lines of evidence from our laboratory and others indicate that tumor aggregate CASR abundance is not predictive of relative calcium responsiveness." (PMID 27537691, 2016).
cancer (83 papers, 2008 to 2026). A tumor composed of atypical neoplastic, often pleomorphic cells that invade other tissues. "The calcium-sensing receptor (CaSR) plays a crucial role in cellular signaling and has been implicated in cancer progression." (PMID 41553706, 2026). "The FLNA protein participates in the regulation of the calcium-sensing receptor and has been associated with increased aggressiveness in a wide range of cancers." (PMID 36900197, 2023). "More functional in vitro and in vivo studies are needed to understand causal links between CaSR genetic variants and cancer progression and/or metastasis." (PMID 34357109, 2021). "We next showed that CASR polymorphisms at the rs1801725 locus are associated with circulating total and ionized calcium levels prior to and after cancer diagnosis in individuals of European descent." (PMID 34357109, 2021). "A correlation was observed between certain CASR rs17251221 type polymorphisms and coronary artery disease, type 2 diabetes, cancer and mortality." (PMID 28122587, 2017). "As CaSR promotes bony metastasis of cancer, this raises the possibility of reducing the risk of such metastases with CaSR-based therapeutics." (PMID 27625611, 2016). "This review will focus on the role of the CaSR in the differentiation and movement of cells, and the mechanisms underlying these processes in the developing CNS and in cancer." (PMID 27303307, 2016). "Examining this polymorphism further, cancer incidence was found to be increased in the recessive model (OR = 4.01; 95% CI = 1.33–12.07; p = 0.042): the homozygous CaSR SS genotype was more frequent in patients than controls." (PMID 18980667, 2008). "We next determined which secondary cancers were associated with the rs1801725 CASR SNP." (PMID 34357109, 2021). "Overall, the expression of CASR variants at rs1801725 in >20% of cancer patients may be linked to the reduced sensitivity of the receptor to calcium, and therefore, the potential for the development of CIH." (PMID 34357109, 2021). "The epigenetic inactivation of the CASR may underlie the reduced CaSR expression in some cancers." (PMID 27679579, 2016). "In addition, the activation of CaSR is associated with an increased expression and secretion of parathyroid hormone-related peptide (PTHrP) which has a role in the development of hypercalcemia in cancer cells." (PMID 26010602, 2015). "The calcium sensing receptor (CASR), a G protein coupled‐receptor, is epigenetically silenced in cancers, and therefore we examined its role in GEP‐NET subtypes." (PMID 39579056, 2025). "Given this multifunctionality, the CaSR also seems to play an important role in cancer development and inflammatory response." (PMID 36467702, 2022). "The extracellular CaSR is widely expressed in the whole body, as the main regulator of calcium homeostasis, and abnormal CaSR function affects the development of cancer." (PMID 36499622, 2022). "CASR was highly expressed in normal tissues and expressed at extremely low levels in each clinical subgroup in cancer tissues." (PMID 36360294, 2022). "What is more important, CaSR has been reported to play a critical role in either promoting or suppressing the progression of several human cancers." (PMID 36348350, 2022). "CircRNA profiling by microarray revealed a potential role of circ_IPCEF1 in PTC and showed interactions with four cancer-related genes, “CASR, CDC25B, NFκB1, and SHOC2” through sponging miR-3619-5p." (PMID 36230649, 2022). "These transfections are necessary because colonic epithelial cells, during transformation into cancer cells, lose their native CaSR expression." (PMID 34576291, 2021). "However, whether the expression of polymorphic CASR variants at these loci, which presumably affects the sensitivity of the receptor to calcium, influences cancer diagnosis at specific pathological sites in patients of European versus African descent remains unclear." (PMID 34357109, 2021).
cancer (continued). "Prior to analyses at specific pathological sites, we assessed the relationship between these SNPs and the CaSR dependent variables, as well as primary cancer and secondary malignancy at all sites as single variables." (PMID 34357109, 2021). "This is quite intriguing as it is the first time to our knowledge where calcilytics have been used in vivo, albeit intratumorally, to directly target tumors where CaSR aids cancer progression." (PMID 32117726, 2020). "An overlooked aspect of the targeting CaSR is its interplay with cytokines and growth factors, which is quite interesting given that they play a significant role in cancer." (PMID 32117726, 2020). "In human PCa tissues, we correlated CaSR expression with cancer cell proliferation and ERG expression that reflect the presence of the fusion gene TMPRSS2-ERG (observed in around half of PCa cases)." (PMID 32252342, 2020). "CaSR staining in cancer cells increases with the stages of PCa progression, from pT2 to pT3 in CLC, then in MCRPC and NEPC." (PMID 32252342, 2020). "CaSR staining was observed on cancer cells in 26% of CLC cases, 25% of MCRPC samples and 100% of NEPC." (PMID 32252342, 2020). "Altogether, it is clear that CasR plays a yin–yang role in cancer, which makes essential to further elucidate the role of this receptor in each cancerous process." (PMID 33113952, 2020). "The extracellular calcium of cancer cells is recognized through the CaSR or the P2X receptor, which manipulates calcium influx and efflux through ion channels or transporters." (PMID 32793401, 2020). "Some studies indicate that CaSR plays a critical role in either suppressing or promoting the progression of several human cancers." (PMID 32671062, 2020). "1,25(OH)2D3 also induces expression of the calcium sensing receptor (CASR) that regulates calcium homeostasis and the differentiation of colon normal epithelium and carcinoma cells." (PMID 32854355, 2020). "The role of CaSR as an inhibitor of the constitutive secretion of various cytokines was detected both in cancer cells and in normal breast cells." (PMID 31847214, 2019). "It is known that Ca levels are usually affected in cancer patients and are related to the calcium sensing receptor (CaSR) and to vitamin D metabolism." (PMID 31534963, 2019). "In other cancers such as breast and prostate cancer, the expression of CaSR has been identified to correlate with an increased affinity of the cancer towards development of bone metastasis." (PMID 29644008, 2018). "Studies have shown that calcium sensing receptor (CaSR) is involved in the progressions of several human cancers." (PMID 29348629, 2018). "Alteration of the function of the CaSR by pharmacological inhibition of its activity e.g. using calcilytic agents has been shown to inhibit cancer cell proliferation and metastasis." (PMID 28764683, 2017). "Disparities in BC outcomes between Caucasian and African American patients as well as the involvement of the CaSR in cancer progression have been amply reported." (PMID 28764683, 2017). "Abnormal CaSR function affects the development of both calciotropic disorders, and non-calciotropic disorders, such as cardiovascular disease and cancer." (PMID 28122587, 2017). "It is possible that a combination of inactivating mutant CaSR expression and progressive increase in circulating cancer cell-derived osteolytic factors contribute to the observed higher circulating calcium in BC cases." (PMID 28764683, 2017). "Our data suggest that dietary calcium is effective in preventing replicative stress, one of the main drivers of cancer and this process is mediated by the calcium-sensing receptor." (PMID 28161520, 2017). "Reports on CaSR expression in human male reproductive system are currently mainly related to cancer." (PMID 27625611, 2016). "The extracellular calcium-sensing receptor (CaSR) is one of the candidates that mediate the cancer preventive effects of dietary calcium." (PMID 27803671, 2016).